ADAM8 (ADAM metallopeptidase domain 8)
Diseases named in the same sentence as ADAM8 in open-access papers (continued):
Sharing a sentence is not in itself a finding about the gene and the disease.
cancer (continued). "When cancer cells are co-cultured with macrophages (THP-1 cells), the expression of LCN2 and MMP-9 has been found to be induced in ADAM8-KO cells, indicating that macrophage signal transduction can override ADAM8-driven intracellular signal transduction in PDAC cells." (PMID 36910158, 2023). "In particular, these 3D cell culture model systems made it possible to study the effects of proteolytic degradation, such as a disintegrin and metalloproteinase 8 (ADAM8), and cell mechanical forces on the restructuring of the ECM environment on cancer cell migration." (PMID 36910158, 2023). "In order to confirm that there exists a specific interplay between ADAM8 expressing cancer cells and fibronectin, we performed the fiber displacement assays in the presence and absence of the ADAM8 specific inhibitor BK-1361 using ADAM8-Ctrl and ADAM8-KD cells." (PMID 37287457, 2023). "Finally, the effect of ADAM8 on the transmigration of cancer cells is not restricted to a single cancer type, it seems to be a rather frequent or general phenomenon." (PMID 36910158, 2023). "However, carcinoma samples with MMP-11 positive MICs showed a more important increase in the mRNA level of 19 factors: IL-1, −5, −6, −8, −17 and −18, ADAM-8, −10, −15, and −23, ADAMTS-1, −2, and −15, IFNβ, MMP-1, as well as mediators related to inflammation (CCL-3, IRAK-4, MyD88 and NFκB)." (PMID 23145063, 2012). "Interestingly, patient primary samples when positive, demonstrated diffuse continuous staining (cytoplasmic and membrane) in the cancer component that was ubiquitous and homogeneous in intensity, unlike ADAM8 staining in cell lines or PDX samples, which was more heterogeneous." (PMID 37568162, 2023). "However, the role of Adam8 in cancer has not been well characterized." (PMID 37370863, 2023). "Two of the genes (KIF17 and ATP8A2) showed no methylation in either cancer or matched tissues, and eight genes (EPHA4, OVOL1, UTF1, ADAM8, BOLL, FOXE3, GUCY1A2, and ADCY5) were equally methylated in the two groups." (PMID 21625442, 2011).
infection (11 papers, 2019 to 2025). The state of being infected such as from the introduction of a foreign agent such as serum, vaccine, antigenic substance or organism. "ADAM8 protein expression was found to be upregulated during the formation of multinuclear giant cells by human salivary gland cells upon infection with human parainfluenza virus type 2 (HPIV2)." (PMID 33392273, 2020). "In male mice, there were 478 DEGs in the infection group (MT) compared with the control group (MC); 122 genes with upregulated expression, such as Ifitm1, Wfdc21, Wfdc17, and Adam8 (P < 0.001); and 356 genes with downregulated expression, such as Tuba1b and Cox7b (P < 0.001)." (PMID 40303139, 2024). "In the lung parenchyma, alveolar macrophages have been shown to contribute significantly to pathogen clearance during infection, and their antimicrobial functions may compensate for the reduction of neutrophils in the alveoli with ADAM8 inhibition." (PMID 35132956, 2022). "Not only viral and bacterial infection may be influenced by ADAM8, but also infection by fungi." (PMID 33392273, 2020). "ADAM10 and ADAM17 together with ADAM8 and ADAM9 seem to be the most relevant ADAM proteases in infection; however, some studies point toward an additional influence of ADAM12, ADAM15, and ADAM33." (PMID 33392273, 2020). "The upregulation of ISG15, CXCL-10, ADAM8, and CSF1 was found after infection with vPdR-36U, which could contribute to the generation of mild CSF forms." (PMID 40006915, 2025).
adenocarcinoma (3 papers, 2014 to 2023). A common cancer characterized by the presence of malignant glandular cells. "TCGA analysis of the identified CAC-related core genes revealed a significant association between high expression of TIMP1 and ADAM8 with low overall survival of patients with both colon (COAD) and rectal (READ) adenocarcinomas." (PMID 36901742, 2023). "Meanwhile, positive ADAM8 was an adverse indicator for both OS and DFS in T3/T4 depth of invasion and N0 stage, and only for DFS in adenocarcinoma, moderately differentiated tumors and male patients." (PMID 25098630, 2014).
inflammation (3 papers, 2021 to 2024). Aberrant reaction of the microcirculation characterized by movement of fluid and leukocytes from the blood into extravascular tissues. "Taken together, we conclude that ADAM8 is important for neutrophil transmigration during pulmonary inflammation in vivo." (PMID 35132956, 2022). "Thus, ADAM8 upregulation is not only part of the acute response but is additionally involved in chronic liver inflammation." (PMID 33814981, 2021).
cardiovascular diseases (1 paper, 2022). "ECH and HF macrophages displayed an increase in Adam8 expression, an important biomarker in cardiovascular diseases, with protective proliferative, pro-survival, and anti-apoptotic properties." (PMID 35203431, 2022).
central nervous system diseases (1 paper, 2024). "ADAM8 is a proteolytic enzyme involved in cleavage of various precursor proteins, signal receptors, and ECMs into their soluble forms, but its role in intracellular signal transduction has not been reported in central nervous system diseases and neurocytes during neuroinflammation." (PMID 38755530, 2024).
immune dysfunction (1 paper, 2025). "For example, ADAM8 and MMP-1 are implicated in T-cell maturation and ECM remodeling, while cathepsins, UPA, and PC9 contribute to immune dysfunction and aging." (PMID 41208973, 2025).
ADAM8 also shares sentences with these, for which no sentence is quoted: multiple myeloma (2 papers); myocardial infarction (2); osteosarcoma (2); astrocytic tumor (1); benign breast disease (1); benign tumors of (1); brain tumor (1); cardia cancer (1); cardiomyopathy (1); Cerebral ischemia (1); chondrosarcoma (1); chronic obstructive pulmonary disease (1); chronic pancreatitis (1); chronic rhinosinusitis with nasal polyps (1); co-infection (1); colon adenocarcinoma (1); COVID-19 (1); dementia (1); ductal adenocarcinoma (1); dysplasia (1); Fasciola infection (1); Fibroadenoma (1); inflammatory bone disease (1); inflammatory breast carcinoma (1); invasive breast carcinoma (1); ischemia (1); Menkes disease (1); neuroblastoma (1); neuropathic pain (1); nonalcoholic steatohepatitis (1).
A further 8 diseases each share a sentence with ADAM8 in 1 paper.